INS (insulin)
Diseases named in the same sentence as INS in open-access papers (continued):
Sharing a sentence is not in itself a finding about the gene and the disease.
diabetes (continued). "For patients with diabetes, self-management programs cover exogenous insulin use (eg, insulin pens), awareness of drug side effects, dietary guidance, and prevention and control education." (PMID 39933171, 2025). "The pancreatic islet cells, particularly the beta cells within them, are often damaged in diabetes, leading to resistance or impaired insulin secretion, which in turn triggers a hyperglycaemic state." (PMID 39931095, 2025). "Through this exercise, we believe this review consolidates cutting-edge innovations on insulin development and diabetes management." (PMID 41155876, 2025). "Diabetes mellitus (DM) is a chronic metabolic disorder characterized by sustained hyperglycemia resulting from either insufficient insulin secretion, impaired insulin action, or both." (PMID 40937349, 2025). "Pancreatic steatosis, or excessive fat deposition in the pancreas, impairs β-cell function in diabetes, particularly type 2, by reducing insulin production and contributing to insulin resistance." (PMID 40760015, 2025). "The origin and etiology of diabetes mellitus can vary significantly, but they consistently involve defects in either insulin secretion or insulin resistance at some stage of disease progression." (PMID 40747308, 2025). "Despite their widespread use, these measures have inherent limitations, particularly in the context of patients with diabetes or those undergoing insulin therapy." (PMID 40687590, 2025). "Research has shown that anti-inflammatory therapies for diabetes can enhance glycemic control and improve insulin secretion." (PMID 40774029, 2025). "Beyond insulin treatment and diabetes management, a consumer-level CGM device (Lingo, Abbott, Abbott Park, IL, USA) has recently been released on the market for use by the general population to monitor glucose fluctuations in relation to lifestyle." (PMID 40648295, 2025). "Molecular pathways, including insulin signaling, AMPK, and mTOR, are implicated in both diabetes and cancer, linking the two diseases further." (PMID 41303679, 2025). "Our case report highlights the reversibility of diabetes secondary to liver transplantation, likely through the recovery of insulin sensitivity (including insulin receptors) and glucose disposal." (PMID 40491591, 2025). "A novel PTD used as an absorption enhancer improved insulin delivery, providing a convenient solution for diabetes treatment." (PMID 40574087, 2025). "The present findings, although preliminary, support the concept that insulin may provide measurable benefit, particularly in patients predisposed to delayed epithelial healing—such as those with advanced keratoconus, ocular surface inflammation, diabetes, or neurotrophic compromise." (PMID 41470103, 2025). "Behaviors were contextualized primarily by insulin (164 cases), by diabetes (16 cases) and, infrequently, as medication or drug use (2 cases)." (PMID 40958557, 2025). "In this review, we will discuss recent advances in understanding lysosome-mediated autophagy and lysosomal proteins involved in maintaining insulin and glucagon homeostasis, as well as their contributions to the etiology of diabetes." (PMID 39996055, 2025). "Since these environmental toxins depend on AhR to exert their toxic effects, AhR is likely to play a role in diabetes development, insulin resistance, and glucose homeostasis." (PMID 40408591, 2025). "Diabetes occurs either due to insufficient insulin production or reduced cellular responsiveness to insulin, resulting in persistent hyperglycemia." (PMID 41010515, 2025). "Zn’s dual role in insulin signaling and oxidative stress regulation underscores its involvement in diabetes pathogenesis." (PMID 41459237, 2025). "Given these limitations, we chose not to rely on BMI but instead adjusted for well-established clinical indicators of obesity, such as diabetes, hypertension, hyperlipidemia, insulin use, and the Charlson Comorbidity Index (CCI)." (PMID 41011280, 2025).
diabetes (continued). "Regarding current diabetes medication, 74 participants (49.3%) were on oral hypoglycaemics, 43 (28.7%) were on both oral hypoglycaemics and insulin, and 33 (22%) were on insulin only." (PMID 40932957, 2025). "This sensor can detect multiple biomarkers related to diabetes, like insulin, which can also be used to differentiate type 1 from type 2 diabetes." (PMID 40422016, 2025). "More than a century from the discovery of insulin, iatrogenic hypoglycaemia remains a major barrier in diabetes care." (PMID 39996361, 2025). "Diabetes mellitus is characterized by hyperglycemia, which results from insulin resistance, inadequate insulin secretion, or dysregulated glucagon secretion." (PMID 39996906, 2025). "Although the results of trials can be conflicting, some studies have shown that hypothalamic insulin action decreases hepatic glucose production and can be a target for new drugs and treatments for diabetes." (PMID 40725728, 2025). "Although several previous studies have reported associations between higher insulin/HOMA indices and cognitive decline, nearly all these studies have also included people with diabetes." (PMID 40478656, 2025). "In contrast, adequate energy availability not only supports protein utilization but also enhances insulin sensitivity and contributes to improved glucose regulation, a key factor in diabetes management." (PMID 41305580, 2025). "Diabetes mellitus (DM) is a chronic metabolic disease characterised by defects in the secretion or function of insulin, the hormone responsible for maintaining stable blood glucose levels." (PMID 41002698, 2025). "Prescribed diabetes medications included the following: metformin, 57.5% (n=417); insulin, 14.9% (n=108); secretagogues, 11.3% (n=82); DPP-4 inhibitors, 8.3% (n=60); sodium–glucose cotransporter-2 inhibitors, 7.9% (n=57); and GLP-1 inhibitors, 5.0% (n=36)." (PMID 40044453, 2025). "Our study provides strong evidence that non-insulin-treated diabetes and hypothyroidism are independent and potentially synergistic drivers of dilated cardiomyopathy (DCM), even after adjustment for age, sex, and cardiovascular comorbidities." (PMID 41153651, 2025). "Another interesting and emerging topic of discussion is insulin's interaction with the cellular nuclei after cellular uptake, which, unfortunately, is often masked by insulin's major therapeutic role in lowering blood sugar levels in diabetes patients." (PMID 41200400, 2025). "Diabetes Mellitus is a group of metabolic diseases marked by persistent high blood sugar levels brought on by impairments in either the action or secretion of insulin or both over a prolonged period." (PMID 40136728, 2025). "The results of cell-based studies demonstrate that resveratrol can alleviate diabetes-related cellular damage by suppressing inflammation, improving insulin signaling, and reducing oxidative stress." (PMID 41378215, 2025). "Since the discovery of insulin in the 1920s, our understanding of diabetes and insulin therapy has advanced significantly." (PMID 41531706, 2025). "This mutation exhibits a dominant-negative effect, leading to progressive diabetes often diagnosed in adolescence and requiring insulin therapy." (PMID 40305339, 2025). "EV miRNAs are known to contribute to diabetes development and progression by facilitating intercellular communication that impacts insulin responsiveness, pancreatic β-cell performance, and inflammatory pathways." (PMID 41446634, 2025). "Insulin initiation in type 2 diabetes mellitus remains challenging despite clear clinical guidelines." (PMID 40897507, 2025). "The purpose of this study was to examine the time-varying nature of risk factors of medication adherence trajectories of aging adults taking chronic medications for hypertension (RASA), hypercholesterolemia (statins), and diabetes (except for insulin)." (PMID 40278536, 2025).
diabetes (continued). "Type 1 diabetes mellitus (T1DM) is due to autoimmune destruction of pancreatic beta cells resulting in inadequate insulin secretion, and type 2 diabetes mellitus (T2DM) is due to endogenous cellular resistance to insulin." (PMID 41262264, 2025). "Diabetes mellitus encompasses a group of metabolic disorders characterized by chronic hyperglycemia due to defects in insulin secretion, insulin action, or both." (PMID 41294602, 2025). "Sinapic acid has been shown to increase insulin-independent glucose uptake in the soleus muscle isolated from rats with STZ-induced diabetes, as well as in L6 skeletal muscle cells cultured under high-glucose conditions." (PMID 40565007, 2025). "Insulin therapy and metformin are commonly prescribed for diabetes management; however, their impact on clinical outcomes in patients with acute viral infections has rarely been investigated." (PMID 40391966, 2025). "Several real-world instances demonstrate how ML is already enhancing diabetes CDSS, from predicting diabetes risk with remarkable accuracy to optimizing insulin dosing and offering personalized guidance to patients based on their real-time blood sugar data." (PMID 40062277, 2025). "Diabetes mellitus is a heterogeneous group of chronic metabolic disorders defined by persistent hyperglycemia due to defects in insulin secretion, insulin action, or both." (PMID 41302978, 2025). "Even with remarkable advances in diabetes technology, such as continuous glucose monitoring systems and automated insulin delivery pumps, a majority of patients fail to meet glycemic targets." (PMID 41202176, 2025). "MAMs have been shown to play a role in insulin signalling and glucose homeostasis, with implications for metabolic disorders such as diabetes." (PMID 39933574, 2025). "The analyses using KEGG database suggest that these genes were involved in diabetes-related, insulin signaling-related, insulin secretion-related, cytokine and chemokine-related and asparate/glutamate-related pathways." (PMID 40855115, 2025). "The patient periodically declined both an insulin pump and sensor, believing his diabetes was stable and noting that his wife, who uses a CGM, often found it alarming for low values." (PMID 41040769, 2025). "Diabetes mellitus is a chronic metabolic disorder characterized by sustained hyperglycemia, resulting from impaired insulin production, insulin action, or both." (PMID 41099986, 2025). "The results showed improved insulin sensitivity and glucose tolerance, showing improvement in glucose metabolism and the potential to help treat diabetes." (PMID 40143179, 2025). "Newly diagnosed diabetes patients described adjusting on demand insulin according to food intake by measuring blood sugar levels often and avoiding certain foods to minimise on demand insulin needs as facilitators to medication self-management." (PMID 40256375, 2025). "A total of 13 988 insulin-treated older adults with diabetes and ADRD were included before propensity score matching, with 1034 CGM users and 12 954 SMBG users." (PMID 41329488, 2025). "These measurements are particularly crucial for individuals managing diabetes and obesity, as they provide insights into how foods influence postprandial glucose responses and insulin levels." (PMID 40026940, 2025). "Insulin resistance results in elevated insulin levels and hyperglycemia, even prior to the onset of diabetes mellitus." (PMID 40564010, 2025). "Diabetes mellitus (DM) is a chronic metabolic disorder characterized by persistent hyperglycemia resulting from impaired insulin secretion, reduced insulin sensitivity, or functional deficiency." (PMID 40822953, 2025). "ZnT8 is almost exclusively expressed in pancreatic β-cells, where it transports zinc into insulin secretory granules, thereby promoting insulin biosynthesis; this has led to intense study of this protein in diabetes research." (PMID 41583444, 2025).
diabetes (continued). "Sphingosine 1-phosphate is known to play a key role in various physiological and pathological processes, including fundamental cellular functions, insulin signaling, and the development of conditions such as diabetes and obesity." (PMID 40551275, 2025). "These pumps have shown promise in applications ranging from cancer therapy, where targeted drug delivery can be maintained, to the management of chronic conditions like diabetes, where insulin release can be fine-tuned to match the patient’s needs." (PMID 40283294, 2025). "Clinical studies in both type 1 and type 2 diabetes patients suggest that regular consumption of camel milk can lower fasting glucose, enhance insulin activity, and potentially decrease the need for exogenous insulin or other diabetes medications." (PMID 41007307, 2025). "This escalating burden underscores the need for effective insulin therapy and continued research to improve diabetes management." (PMID 39930590, 2025). "A 70-year-old female with a past medical history of type 2 diabetes mellitus (treated with insulin), hypertension, and bipolar disorder was admitted to the Intensive Care Unit after suffering cardiac arrest post-seizure." (PMID 41589173, 2025). "Autophagy plays a crucial role in the homeostatic activity of pancreatic β-cells, and failures in autophagic mechanisms lead to pancreatic degeneration, impaired insulin secretion, and glucose intolerance, all hallmarks of diabetes." (PMID 40605977, 2025). "Diabetes mellitus is a chronic metabolic disease characterized by raised blood glucose levels due to insufficient insulin production by the pancreas, insulin resistance, or both." (PMID 40822470, 2025). "The first scale specifically developed to measure patients’ numeracy skills in diabetes management was the Diabetes Numeracy Test, which tested the ability to read nutrition labels, determine the insulin glucose ratio and calculate correction factors." (PMID 39999057, 2025). "We adjusted for potential confounders that influenced glycemic variability (e.g., age, sex, duration of diabetes, and use of insulin)." (PMID 41497478, 2025). "Diabetes mellitus (DM) is a chronic metabolic disorder characterized by abnormally high glucose levels due to impaired insulin action and/or production." (PMID 40679946, 2025). "Islet transplantation presents a hopeful therapeutic strategy for managing diabetes by reinstating insulin secretion and achieving improved glycemic control." (PMID 41471742, 2025). "Diabetes mellitus is a metabolic disorder characterized by insufficient insulin production or impaired insulin responsiveness, leading to abnormally high blood glucose levels." (PMID 41345744, 2025). "Patients with diabetes, characterized by elevated fasting insulin levels, higher HOMA-IR values, and increased C-peptide levels, are more likely to develop endometrioid endometrial carcinoma (EEC)." (PMID 41440200, 2025). "In contrast to inflammation, HPSE-1 expressed by donor T cells played a key role in the induction of diabetes by allowing autoimmune T cells to traverse peri-islet BMs in order to destroy insulin-producing beta cells." (PMID 40362360, 2025). "In the present study, 63% of patients with sepsis had elevated blood glucose levels, requiring intravenous insulin therapy, although only one-third of the sample had a prior history of diabetes." (PMID 40779693, 2025). "Nonetheless, both in healthy individuals and those with diabetes, its primary mode of action appears to involve an augmentation of insulin secretion from the islets of Langerhans and a reduction in the metabolic clearance rate of insulin." (PMID 39787127, 2025). "Diabetes mellitus (DM) is a chronic metabolic disorder characterized by persistent hyperglycemia, which arises from impaired insulin secretion, diminished insulin action, or a combination of both mechanisms." (PMID 40954177, 2025).
diabetes (continued). "Mean age, HbA1c, BMI, diabetes duration, BP, lipid profile, obesity staging categories and smoking rates were similar, as were proportions on lipid‐lowering medication and insulin between AMOS trial groups." (PMID 39511718, 2025). "When people with diabetes who use insulin (PWDI) move between different parts of the healthcare system, there are many challenges to managing insulin safely." (PMID 40324886, 2025). "Overactivation of these pathways contributes to oxidative stress and endothelial dysfunction in hypertension, lipid imbalances in dyslipidemia, mitochondrial damage in chronic kidney disease and insulin signaling impairment in diabetes." (PMID 40980166, 2025). "Regarding insulin-related knowledge, nurses also demonstrated good knowledge except for the symptoms of ketoacidosis (62.3%), onset time of intermediate-acting insulin (72.6%), and causes of hyperglycemia (73.5%)." (PMID 41573793, 2025). "Two single case reports describe remission of diabetes post‐liver transplant in patients with insulin‐dependent diabetes with normalization of HbA1c and discontinuation of insulin and oral anti‐glycaemic agents." (PMID 40664615, 2025). "According to the World Health Organization (WHO), diabetes mellitus (DM) is a chronic metabolic disorder characterized by the pancreas’s inability to produce sufficient insulin or the body’s ineffective use of insulin." (PMID 40922753, 2025). "Exosomes enriched with a variety of growth factors, proteins, and miRNAs have been found to reverse insulin resistance, alleviate β cell apoptosis, and restore insulin secretion in the treatment of diabetes and its complications." (PMID 39757599, 2025). "Diabetes management has been transformed by insulin pumps, which provide a more precise and individualized insulin delivery method compared to conventional injection therapies." (PMID 40465596, 2025). "One desirable effect sought in compounds in development for diabetes therapy is their insulin-mimetic action, to rapidly improve glycemic control." (PMID 39861427, 2025). "Activation of PPARγ by specific agonists, thiazolidinediones such as pioglitazone, has been widely used to treat diabetes by insulin-sensitizing and pancreatic β-cell preserving effects." (PMID 40356984, 2025). "Diabetes mellitus (DM) is a chronic metabolic disease characterized by persistent hyperglycemia due to impaired insulin secretion, action, or both." (PMID 40742490, 2025). "Diabetes is a metabolic disorder characterized by hyperglycemia that results from disturbed insulin secretion or insulin resistance." (PMID 39852351, 2025). "Restoring damaged beta cells to insulin production or prompting other pancreatic cells to secrete insulin is an essential goal of diabetes research." (PMID 40365181, 2025). "In diabetes, the insulin sensitivity was more strongly reduced (SPINA-GR: 0.61 vs. 1.41 mol/s, p = 0.0057) and the insulin resistance increased (HOMA-IR: 7.3 vs. 3.2, p = 0.017)." (PMID 40217596, 2025). "Diabetes is characterized by persistent hyperglycemia resulting from insufficient insulin secretion or impaired insulin utilization, which over time causes damage to multiple organ systems." (PMID 41277984, 2025). "Ficus pumila L. extract can improve insulin secretory capacity and insulin resistance in post-COVID-19 infection-induced diabetes." (PMID 39861420, 2025). "GLP-1 receptor agonists are among the most effective non-insulin medications for lowering hemoglobin A1c (HbA1c) and often demonstrate a greater reduction in HbA1c compared to other classes of diabetes medications." (PMID 41299410, 2025). "Treatment of diabetes mellitus (DM) in cats relies upon the administration of exogenous insulin or a sodium‐glucose cotransporter‐2 inhibitor (SGLT2i), along with dietary modification and mitigation of insulin‐resistant disorders." (PMID 40105430, 2025).